GPX1 (glutathione peroxidase 1)
Diseases named in the same sentence as GPX1 in open-access papers (continued):
Sharing a sentence is not in itself a finding about the gene and the disease.
colon cancer (8 papers, 2013 to 2023). "Silencing of antioxidative enzymes such as catalase (CAT) or glutathione peroxidase-1 (GPx-1) maintained colon cancer cells in a senescent state." (PMID 36230727, 2022). "Altogether, these data showed that, in contrast to CAT and GPx-1, HO-1 expression was downregulated upon the induction of senescence in colon cancer cells." (PMID 36230727, 2022). "The expression products of GPX1 mainly exist in lung, liver, kidney and other tissues with high oxygen tension, and GPX1 expression is up-regulated in breast, lung and colon cancer tissues, which may be conducive to tumor progression and spread." (PMID 38180104, 2023). "Interestingly, when we silenced CAT and GPx-1 in senescent colon cancer cells with specific siRNAs and treated these cells with hemin, we observed that the expressions of cyclins, especially cyclin B, were reduced." (PMID 36230727, 2022). "Here, we demonstrated that, upon the induction of senescence with IRINO, the expression of CAT and GPx-1, enzymes that utilize H2O2, was strongly upregulated in colon cancer cells." (PMID 36230727, 2022). "Taken together, these data suggest that the silencing of antioxidative enzymes—HO-1, CAT, and GPx-1—maintains colon cancer cells in a non-proliferating, epithelial state with increased mechanisms of DNA protection." (PMID 36230727, 2022). "In the present study, we showed that the induction of senescence in colon cancer cells led to the upregulation of two enzymes involved in H2O2 utilization, catalase, and glutathione peroxidase-1 but the downregulation of heme oxygenase-1, heme degrading enzyme." (PMID 36230727, 2022). "As expected, the GPx-1 activity and expression were significantly enhanced after the addition of medium-high dosed TGF-β1, which was also coincident with the previous studies in colon cancer cells." (PMID 31358027, 2019). "We recently reported that ectopic expression of SBP1 was sufficient to cause an approximately 50% reduction in the activity of the GPx-1 selenoprotein in human HCT116 colon cancer cells without affecting GPx1 mRNA and protein levels." (PMID 24163737, 2013).
COVID-19 (8 papers, 2020 to 2025). A disease caused by infection with severe acute respiratory syndrome coronavirus 2. "The previous findings on higher levels of both fibrinogen and D-dimmer in COVID-19 patients carriers of the variant GPX1*T allele also implicate the consequential effect of this polymorphism on coagulation." (PMID 37373377, 2023). "COVID-19 patients homozygous for variant GPX1*Leu/Leu had the highest levels of fibrinogen as well, but the significance was borderline (p = 0.089)." (PMID 35361071, 2022). "On the other hand, it seems that polymorphic GPX1 expression influences coagulation, since we found that COVID-19 patients with low-activity GPX1*Leu allele had higher levels of both fibrinogen and D-dimmer." (PMID 35361071, 2022). "Furthermore, the influence of SOD2 and GPX1 polymorphisms on the inflammation and coagulation parameters in COVID-19 patients was also found." (PMID 37373377, 2023). "Additionally, we have found that polymorphisms of SOD2 rs4880 and GPX1 rs1050450 influence COVID-19 patients’ laboratory biochemical profile." (PMID 35361071, 2022). "Furthermore, we have shown the influence of SOD2 and GPX1 polymorphisms on the inflammation and coagulation parameters in COVID-19 patients." (PMID 35624818, 2022). "Larger studies are needed to confirm whether GPX1 polymorphism can serve as a biomarker of increased susceptibility to enhanced coagulation in COVID-19." (PMID 35361071, 2022). "Polymorphisms of SOD2 and GPX1 influenced COVID-19 patients’ laboratory biochemical profile: SOD2*Val allele was associated with increased levels of fibrinogen (p = 0.040) and ferritin (p = 0.033), whereas GPX1*Leu allele was associated with D-dimmer (p = 0.009)." (PMID 35361071, 2022). "Hence, it could be speculated that recovered COVID-19 patients, who are carriers of referent GPX1 or GPX3 alleles, are more prone to developing LV diastolic impairment." (PMID 37373377, 2023). "Our findings regarding the influence of SOD2 and GPX1 polymorphisms on the laboratory biochemical parameters might be of clinical importance, since we found that COVID-19 patients with low-activity alleles of these genes have higher levels of inflammation and coagulation parameters." (PMID 35361071, 2022). "The interaction between GPx1 and Mpro, the main protease necessary for viral replication, is currently gaining attention as a potential therapeutic agent for COVID-19." (PMID 35563199, 2022). "Ebselen, a selenium-containing GPx1 mimetic, has emerged as the strongest inhibitor of Mpro and a target of great interest for therapeutic interventions for COVID-19." (PMID 35563199, 2022). "SOD2 and GPX1 genotypes independently did not seem to significantly affect the risk for COVID-19 development as well." (PMID 35361071, 2022). "However, our results on the lack of association of GPX1 polymorphism with susceptibility to COVID-19 are not in favor of the presumption that GPX1 acts as a Mpro inhibitor." (PMID 35361071, 2022). "Serum from patients with severe COVID-19 significantly upregulated genes involved in the cellular antioxidant response in HUVEC, including NFE2L2, HMOX1, SOD1, CAT, GPX1, and GSR." (PMID 41583455, 2025). "The examined polymorphisms of Nrf2, SOD2, GPX1 and GPX3 in our study also did not have association with severity of COVID-19 (Table A1)." (PMID 35361071, 2022).
Hepatic steatosis (8 papers, 2014 to 2026). Steatosis is a term used to denote lipid accumulation within hepatocytes. "GPX1 encodes a key gene of oxidative stress management, and it is also a potential drug target in hypertension and metabolic-associated fatty liver disease." (PMID 41010012, 2025). "The PPIs could help explain partially a puzzling observation that knockouts of Sod1 and Gpx1, two genes encoding redox enzymes with similar functions in scavenging free radicals, led to different severities in many phenotypes, including hepatic steatosis." (PMID 36834640, 2023). "Further investigation using a conditional knockout approach will help clarify the role of GPx1, if any, in fatty liver disease." (PMID 24672550, 2014). "Interestingly, mice with whole body deficiency of GPx1, a key enzyme in ROS detoxification, fail to become obese mice on a high-fat diet, do not develop hepatic steatosis, and have improved hepatic insulin signalling." (PMID 24672550, 2014). "Compared with HFHC, both CAB and HECAB reduced serum insulin and HOMA-IR, attenuated hepatic steatosis, increased SOD1 and CAT, and reduced NF-κB, IL-6, TNF-α, and IL-1β, whereas GPx1 remained unchanged." (PMID 42193214, 2026). "At the same time, a high fat and sucrose diet in mice with GPX haploinsufficiency (Gpx1+/−) did not aggravate adiposity, but resulted in an adverse metabolic profile characterized by more pronounced glucose intolerance, dyslipidemia, hepatic steatosis, and cardiac fibrosis." (PMID 32344656, 2020).
melanoma (8 papers, 2018 to 2025). A malignant, usually aggressive tumor composed of atypical, neoplastic melanocytes. "The presence of the GPX1 T variant allele contributes to an increased risk of melanoma and meningioma." (PMID 34200699, 2021). "The genes are not regulating each other and loss of SELENBP1 and over-expression of GPX1 eventually are independent events during melanoma progression." (PMID 29535818, 2018). "In vitro, it reduced C32 melanoma cells’ viability, affecting the mRNA expression of the antioxidant enzymes superoxide dismutase-1 and glutathione peroxidase-1." (PMID 40364408, 2025). "In the present study, it was found that the addition of the studied flavones caused oxidative stress in the melanoma cells, for which there was also an increase of the SOD1, SOD2, GPX1 and CAT gene expression." (PMID 35059971, 2022). "As it was published in literature that SELENBP1 and GPX1 are influencing each other, directly, we transfected melanoma cell lines with siRNA against GPX1 or an over-expression construct for SELENBP1, respectively." (PMID 29535818, 2018). "Geoprofile data revealed significantly elevated levels of GPX1 expression on an mRNA level in malignant melanoma (MET), compared to normal skin; protein expression data confirmed this finding." (PMID 29535818, 2018). "The re-expression of SELENBP1 combined with down-regulation of GPX1 expression led to reduction of the proliferation of melanoma cells." (PMID 29535818, 2018). "Besides, iNOS, SOD1, NOX4, PRX3, PXDN and GPX1 are generally increased during melanoma progression, while CAT, GPX3, TXNIP and PRX2 are decreased." (PMID 35326089, 2022). "However, simultaneous SELENBP1 over-expression plus GPX1 knockdown reduces melanoma cell proliferation significantly." (PMID 29535818, 2018). "Low SELENBP1 mRNA levels correlate inversely with GPX1 expression in melanoma." (PMID 29535818, 2018). "According to our analysis, 66% of the isoforms presented differential expression on melanoma progression: NOS2, SOD1, NOX4, PRX3, PXDN and GPX1 are increased during melanoma progression, while CAT, GPX3, TXNIP, and PRX2 are decreased." (PMID 35326089, 2022). "GPX1 and LPXN have been reported to play crucial roles in multiple cancer types, including melanoma." (PMID 30779739, 2019). "Western blot analysis of radial growth phase (RGP), vertical growth phase (VGP), primary tumors which were not classified (PT) and melanoma metastasis (MET) cell lines showed high GPX1 expression in 16 of 18 tested cell lines." (PMID 29535818, 2018). "The two melanoma cell lines WM1158 and WM9 showed highest SELENBP1 expression without inverse correlation to GPX1 protein amount." (PMID 29535818, 2018).
thyroid cancer (8 papers, 2015 to 2023). "In fact, the decrease in the antioxidant enzymes GPx1 and TrxR1 found in thyroid cancer suggest that the antioxidant systems of thyroid cancer cells are not able to adequately counteract the effect of free radicals." (PMID 32471147, 2020). "This study elucidates the mechanism involved in the antioxidant/oxidant system in thyroid cancer, focusing the attention on the role played by selenoproteins GPx1 and TrxR1." (PMID 29371830, 2018). "Here, we further characterize the role of oxidative stress in thyroid cancer by analyzing the expression of two selenium antioxidant molecules, glutathione peroxidase (GPx1) and thioredoxin reductase (TrxR1) in thyroid cancer cells." (PMID 29371830, 2018). "The intensity of the band detected by the anti-GPx1 antibody in thyroid cancer tissue was lower for all patients than those detected in healthy tissue." (PMID 29371830, 2018). "Our results show a decrease in the expression of GPx1 and TrxR1 (− 45.7 and − 43.2% respectively, p < 0.01) in the thyroid cancer cells compared to the healthy cells." (PMID 29371830, 2018). "On the other hand, low GPX1 expression was reported in thyroid cancer." (PMID 34943522, 2021). "In addition, we have also shown in thyroid cancer a reduction of the expression of glutathione peroxidase (GPx1) and thioredoxin reductase (TrxR1), two seleno-enzymes with antioxidant action." (PMID 32471147, 2020). "It has been demonstrated that the PIM-1 kinase increases the protein expression of the antioxidants GPX1 and SOD2 in thyroid cancer cells, whereas its inactivation increases ROS." (PMID 35682803, 2022). "Interestingly, the increased expression of GPX1 and SOD2 and augmented GPX and SOD activities have been reported in thyroid cancer when compared with normal tissue." (PMID 35682803, 2022). "Western blot analyses showed a decrease in GPx1 and TrxR1 expression in thyroid cancer, without a real quantification of the difference." (PMID 29371830, 2018). "Glutathione peroxidase family showed variable gene expression: GPX1 and GPX2 expression analysis suggested minor increase in mRNA synthesis, GPX3, GPX5, and GPX7 expression was downregulated in thyroid cancers, whereas GPX4 expression did not change." (PMID 26664298, 2015).
dyslipidemia (7 papers, 2016 to 2024). "Our findings indicate that the expression of Gpx1 in the skeletal muscle is sensitive to the unstable redox environment associated with severe dyslipidemia and exercise." (PMID 27010651, 2016). "Of these genes, only Gpx1 exhibited changes in DNA methylation associated with dyslipidemia and exercise: we observed both increased DNA methylation with dyslipidemia and a transient decrease in DNA methylation with exercise." (PMID 27010651, 2016). "Downregulation of Gpx1, Pparα, and Sod1 transcripts by HFD exposure and mixed HFD and PM2.5 exposure affects this pathway, increasing the risk of dyslipidemia." (PMID 39766314, 2024). "In conclusion, Gpx1 expression in the mouse skeletal muscle can be altered by both exercise and dyslipidemia through changes in DNA methylation, leading to a fine regulation of free radical metabolism." (PMID 27010651, 2016). "An interesting finding is that although Gpx1 expression responds to both dyslipidemia and exercise, only changes in methylation are detected with dyslipidemia and not exercise, at least not in the long-term." (PMID 27010651, 2016). "Expression of Sod2, Txr1, Prdx3 and Gpx1 was altered by 3 months of exercise and/or severe dyslipidemia in 6-mo dyslipidemic mice." (PMID 27010651, 2016). "In addition, large randomized controlled trials must confirm whether excess selenium and GPX1 may contribute to dyslipidemia." (PMID 37132140, 2024).
heart failure (7 papers, 2018 to 2023). Inability of the heart to pump blood at an adequate rate to meet tissue metabolic requirements. "Oxidative stress factors, such as Sod2, GPX1, etc., can efficiently suppress apoptosis of the myocardial cells and prevent the LPS-induced cardiac insufficiency and death." (PMID 30413180, 2018). "The supplementation of selenium which is an essential trace element showed obvious cardioprotective effects toward advanced glycation end products (AGEs)-induced heart failure via inhibiting DNMT2-induced DNA methylation of glutathione peroxidase 1 (GPX1) gene promoter in myocytes." (PMID 36093141, 2022). "In DOX-induced heart failure mice, SOD2, GPx-1, FOX3a, and SIRT3 expression are decreased, apoptotic cells and cleaved-caspase-3 expression are increased, as well as inflammatory cytokines such as IL-1β, IL-6, and TNF-α are increased." (PMID 34513812, 2021).
ileocolitis (7 papers, 2010 to 2024). Ileocolitis or ileal Crohn's is the most common type of Crohn's disease. "Genetic background affects susceptibility to ileocolitis in mice deficient in two intracellular glutathione peroxidases, GPx1 and GPx2." (PMID 20976020, 2010). "Notwithstanding the limitations related to potential linkage disequilibrium and difficulties in meeting assumptions of Mendelian randomization, in a specific Gpx1-null and Gpx2-null murine model (B6), the development of ileocolitis was facilitated." (PMID 39202524, 2024). "Previous analyses have shown that a double knockout of GPx1 and GPx2 results in spontaneous ileocolitis." (PMID 23977205, 2013). "This is consistent with the spontaneous ileocolitis and intestinal cancer in GPx1/GPx2 double-knockout mice." (PMID 23977205, 2013). "Mice deficient in the glutathione peroxidase isoenzymes, GPX1 and GPX2 (Gpx1/2-Double Knock Out [DKO]) have spontaneous ileocolitis that is driven by gut microbiota." (PMID 22970191, 2012). "The C57BL/6 (B6) GPx1/2 double-knockout (DKO) mice have mild ileocolitis, and 129S1/Sv DKO mice have severe inflammation." (PMID 20976020, 2010). "In the mouse, combined deficiency of GPX1 and GPX2 pre-disposes to ileocolitis." (PMID 39536393, 2024). "In addition, GPx1/GPx2 double KO mice spontaneously developed an ileocolitis." (PMID 31765890, 2020). "We previously showed germ‐free Gpx1/2‐DKO mice of mixed B6.129 background did not develop ileocolitis." (PMID 32810389, 2020). "In GPx1-GPx2 double KO animals, only the re-introduction of GPx2 but not of GPx1 was able to rescue the phenotype of spontaneous ileocolitis and subsequent intestinal cancer formation." (PMID 31765890, 2020). "These GPx1/2-double knockout (DKO) mice (on a mixed C57BL/6 and 129S1/Sv genetic background) have microflora-dependent ileocolitis, since germ-free mice do not have inflammation." (PMID 20976020, 2010).
myocardial infarction (7 papers, 2008 to 2025). Gross necrosis of the myocardium, as a result of interruption of the blood supply to the area, as in coronary thrombosis. "In addition to upregulating antioxidant genes such as Gpx1 (Glutathione peroxidase 1), it also upregulates angiogenesis and arteriogenesis after myocardial infarctions (MIs) through VSMC proliferation and EC migration." (PMID 39941130, 2025). "The potential importance of this finding is shown in prospective cohort studies that found a low level of erythrocyte GPx-1 activity was associated with increased risk of nonfatal myocardial infarction or death from cardiovascular causes in patients with CAD." (PMID 18629312, 2008). "Recent studies in human have shown that decreased GPX-1 activity was observed in patients with coronary artery disease (CAD) and those with acute myocardial infarction." (PMID 20735837, 2010). "Nonetheless, mice overexpressing Gpx1 display enhanced survival following myocardial infarction, and while infarct size was not reduced, Gpx1-overexpressing mice display enhanced ventricular function with less cardiomyocyte death." (PMID 31857574, 2019). "Other studies show that GPX1 activity in washed erythrocytes is inversely correlated with CAD and acute myocardial infarction (MI)." (PMID 35883899, 2022). "GPx-1 activity of erythrocytes has a prognostic consequence for cardiovascular diseases (CVD), since a significant negative relationship between the risk of heart attacks and determined GPx-1 activity has been shown to exist." (PMID 26473024, 2015).
pancreatic cancer (7 papers, 2018 to 2023). "Like GPx1-3, GPx4 is also a tumor suppressor due to its down-regulation in breast cancer and pancreatic cancer." (PMID 38202704, 2023). "Exogenous murine REG2 protein inhibited the proliferation of Gpx1-/- and Sod1-/- islets and decreased cell viability of human pancreatic cancer cells (PANC1)." (PMID 37107224, 2023). "Both in vitro and in vivo assays demonstrated that GPX1 silencing drives a mesenchymal transition phenotype and gemcitabine resistance by activating the ROS-mediated Akt/GSK3β/Snail signaling axis in pancreatic cancer cells." (PMID 35626163, 2022). "GPX1 overexpression slows pancreatic tumor growth in vitro and in vivo and GPX1 gene delivery is proven to be beneficial for pancreatic cancer treatment." (PMID 35626163, 2022). "Tissue microarray analysis showed that GPX1 expression is significantly down-regulated in pancreatic cancer tissues compared with adjacent tissues, predicting poor patient prognosis." (PMID 35626163, 2022). "GPX1 immunoreactivity was also decreased in four pancreatic cancer cell lines when compared to a normal pancreas." (PMID 35626163, 2022). "Currently, several studies have supported the role of GPX1 as a tumor suppressor in pancreatic cancer." (PMID 35626163, 2022). "In contrast, in pancreatic cancer patients, the expression of Gpx-1 is decreased." (PMID 37242524, 2023). "Moreover, GPX1 is downregulated in most pancreatic cancer cell lines compared with pancreatic ductal epithelial cells." (PMID 35626163, 2022). "On the other side, increased GPX1 levels activated apoptosis in pancreatic carcinoma." (PMID 34943522, 2021). "It is currently known that the GPX1 expression level in tumor tissues is negatively correlated with the overall survival time of patients with breast, gastric, and glioma cancers and leukemia but is correlated with a favorable prognosis in pancreatic cancer patients." (PMID 35626163, 2022). "GPX1 levels in both human pancreatic cancer specimens and cell lines are also lower than those in a normal pancreas." (PMID 35626163, 2022).